EGFR (epidermal growth factor receptor)
Diseases named in the same sentence as EGFR in open-access papers (continued):
Sharing a sentence is not in itself a finding about the gene and the disease.
osteosarcoma (continued). "Functionality of EGFR in osteosarcoma cells was proven by EGF-mediated activation of both MAPK and PI3K/AKT pathway (determined by phosphorylation of ERK1/2, AKT, S6, and GSK3β)." (PMID 26526352, 2015). "Expression of erbB molecules, especially the epidermal growth factor receptor (EGFR, erbB1), has been described in osteosarcomas." (PMID 26526352, 2015). "The respective EGFR mRNA was detectable by real-time PCR in all osteosarcoma cell lines and correlated roughly with membrane-residing EGFR levels." (PMID 26526352, 2015). "Next, the effect of EGFR blockade by gefitinib on osteosarcoma cell migration was determined using trans-well assays." (PMID 26526352, 2015). "We also found that EGFR was expressed in all of three osteosarcoma cell lines used in this study, though the EGFR protein level in U2OS cells was markedly lower than in other two cell lines." (PMID 26050198, 2015). "EGFR-mediated survival signals protect human osteosarcoma cells against cellular stress conditions including several antineoplastic drugs." (PMID 26526352, 2015). "In this paper, we also found that the combinative treatment with COX-2 inhibitor celecoxib and EGFR inhibitor ZD6474 presented a synergistic/additive antitumor effect on osteosarcoma in vivo and in vitro." (PMID 26050198, 2015). "The indicated osteosarcoma cells exhibited significantly reduced migratory potential following EGFR inhibition leading to elongated time frames of transmembrane passage." (PMID 26526352, 2015). "Using molecular and pharmacological approaches, we also found that the AREG-induced cell migration of osteosarcoma cells was mediated by EGFR signaling through its downstream PI3K/Akt pathway." (PMID 26503469, 2015). "At serum-reduced conditions, EGFR inhibition by gefitinib induced marked apoptotic osteosarcoma cell death." (PMID 26526352, 2015). "We have investigated a panel of human osteosarcoma cell lines regarding EGFR expression and downstream signalling." (PMID 26526352, 2015). "Accordingly, activation of PI3K/AKT pathway and osteosarcoma cell migration was recently demonstrated by endogenous expression of transforming growth factor α via binding to EGFR." (PMID 26526352, 2015). "In order to determine functionality of EGFR in osteosarcoma cells we selected four cell lines (HOS, MG-63, OS-10, IOR-MOS) with high EGFR expression for signal transduction analysis." (PMID 26526352, 2015). "Various overexpressed cell surface transmembrane receptors, such as ErbB2, EGFR, IGF-1R, PDGFR and VEGFR, activate diverse signaling cascades that have been implicated in osteosarcoma oncogenesis." (PMID 26050198, 2015). "We have previously demonstrated that the cytotoxic activity of NK cells can be enhanced and directed to osteosarcoma cells by anti-EGFR cetuximab." (PMID 24612598, 2014). "Only one study simultaneously examined the status of EGFR and four downstream molecules - pSTAT3, pERK1, pAkt, survivin - by IHC in 47 samples of conventional osteosarcomas." (PMID 25146150, 2014). "While LPS + IFN-γ–activated M2-like macrophages had low anti-tumor activity, IL-10–polarized M2-like macrophages were able to reduce osteosarcoma cell growth in the presence of the anti-EGFR cetuximab involving antibody-dependent tumor cell phagocytosis." (PMID 24612598, 2014). "GAK is overexpressed in U2OS osteosarcoma cells, which lack EGFR expression, and knockdown of GAK inhibits their proliferation." (PMID 24971999, 2014). "Antibody-dependent cell conjugate formation and inhibition of tumor cell growth were only observed for half of the osteosarcoma cell lines despite significant EGFR expression." (PMID 24612598, 2014). "The procedure was tested with the EGFR expressing osteosarcoma cell line HOS and samples of kidney carcinoma tissue." (PMID 22348285, 2012).
osteosarcoma (continued). "After applying the molecular docking technique and referring to several studies, we speculated that DUSP3 affects the stemness of osteosarcoma cells by regulating EGFR." (PMID 39744427, 2025). "Targeting the EGFR/STAT3/SOX2 axis may be a promising therapeutic approach for treating osteosarcoma." (PMID 39744427, 2025). "Among these core targets, EGFR (48-sided), CASP3 (47-sided), ESR1 (42-sided), HSP90AA1 (42-sided), SRC (42-sided) and IGF1 (40-sided) have high nodes, indicating that they are closely associated with PA anti-osteosarcoma dense mechanisms." (PMID 40991530, 2025). "Targeting DUSP3 and the EGFR/STAT3/SOX2 axis may offer a new therapeutic approach for treating osteosarcoma." (PMID 39744427, 2025). "This study revealed the correlation between PD-L1, STAT3, and EGFR, which may indicate the role of STAT3 and EGFR in PD-L1 regulation in osteosarcoma." (PMID 38434518, 2024). "Moreover, DATS treatment led to the inactivation of the EGFR/PI3K/AKT/mTOR pathway in osteosarcoma cells." (PMID 38434350, 2024). "Therefore, EGFR is a prospective therapeutic target in this research for the treatment of osteosarcoma." (PMID 38338373, 2024). "This may become the basis of further research targeting STAT3 and EGFR in addition to PD-1/PD-L1 immunotherapy in osteosarcoma." (PMID 38434518, 2024). "While it has been shown to inhibit the expression of epidermal growth factor receptor (EGFR) in various cancers, its effects on osteosarcoma (OS) cells remain unclear." (PMID 38434350, 2024). "The role of EGFR (HER1) in osteosarcoma has also attracted attention." (PMID 39015499, 2024). "MiR-491-5p has been reported to suppress tumor growth in osteosarcoma by reducing EGFR expression." (PMID 38434350, 2024). "The existence of a correlation between PD-L1, STAT3, and EGFR indicates the potential role of STAT3 and EGFR in PD-L1 regulation in osteosarcoma, which may become the basis for targeted therapy." (PMID 38434518, 2024). "Specifically, the treatment of ononin induces apoptosis, inhibiting cell proliferation, invasion, migration, and metastasis via blocking MMP2/9 expression and EGFR-Erk1/2 pathways, which was further validated using biomarkers in human osteosarcoma MG-63 xenograft mice." (PMID 36765716, 2023). "Further, some gene targets already investigated in the ACT of osteosarcoma, including B4GALNT1 (encoding beta‐1,4‐N‐acetyl‐galactosaminyltransferase 1 involved in the biosynthesis of GD2), ERBB2, and EGFR, also showed low expression in osteosarcoma compared with adjacent normal tissues." (PMID 37457661, 2023). "AZD3759 could inhibit the proliferation and progression of osteosarcoma through the blockade of the EGFR and JAK pathways." (PMID 37091161, 2023). "Thus, our study reveals the discovery of a simple dual-targeting strategy that yields a molecule, ZR2002, with unique potency against osteosarcoma cells expressing various levels of EGFR." (PMID 36980255, 2023). "To verify this hypothesis, we chose to study the effects of these drugs in vitro on a high-mortality tumor cell type, the Saos-2 osteosarcoma cell line expressing EGFR, and in vivo in a corresponding xenograft model." (PMID 36980255, 2023). "However, as osteosarcoma cells express EGFR, the combination of gefitinib with chemotherapy has been reported to increase antitumor cell growth in vitro." (PMID 36980255, 2023). "Expression of EGFR has frequently been observed in high-grade osteosarcomas." (PMID 35337159, 2022). "Moreover, when epidermal growth factor receptor was silenced by short hairpin RNA in implanted osteosarcoma cells, tumor growth stimulated by recruited and polarized macrophages was suppressed." (PMID 35720360, 2022). "It has also been shown that inhibiting EGFR in human osteosarcoma cell lines may effectively reduce cell migration, invasion, and colony formation in these cells." (PMID 36234645, 2022).
osteosarcoma (continued). "Therefore, we used a human EGFR Alexa Fluor 647-conjugated antibody to recognize and specifically target proteins expressed on the surface of osteosarcoma tumor cells." (PMID 36234645, 2022). "Notably, epidermal growth factor receptor (EGFR) is reported to be overexpressed in osteosarcoma and, for that reason, is targeted by a human EGFR antibody conjugated to our novel targeted multifunctional radio-nanotherapeutic." (PMID 36234645, 2022). "In conclusion, our researchuncovered an important role of the cir-ITCH/miR-7/EGFR pathway in themigration and invasion of osteosarcoma cells and suggested that cir-ITCHmay be a prognostic marker and a promising therapeutic target for osteosarcoma." (PMID 31960764, 2020). "We and others have reported that EGFR was overexpressed in many types of osteosarcomas and STSs." (PMID 32002123, 2020). "Although inhibiting EGFR with gefitinib has been successful in the clinical treatment in a subset of non-small cell lung cancer, it has not been effective in inhibiting proliferation or survival in osteosarcoma cell lines on its own." (PMID 32961800, 2020). "EGFR (Her1) has also been suggested to play a role in the pathogenesis of osteosarcoma." (PMID 32961800, 2020). "Ewing’s sarcoma and osteosarcoma also have a significant percentage of EGFR overexpression, which may contribute to their observed innate resistance to prexasertib." (PMID 35582228, 2020). "The present study tested the hypothesis that cantharidin abrogates feedback STAT3 activation induced by EGFR inhibition in osteosarcoma, resulting in enhanced tumor suppression upon combined SC and erlotinib treatment." (PMID 31422383, 2019). "Altogether, these results indicate that CYR61 expression level associates with IGF1Rβ but not with EGFR or PDGFR expression in osteosarcoma." (PMID 30642298, 2019). "Therefore, preventing STAT3 phosphorylation is an enticing strategy to defeat resistance to EGFR inhibitors such as erlotinib in various tumor types, including relapsed or refractory osteosarcoma." (PMID 31422383, 2019). "Several reports have demonstrated that EGFR is expressed at high levels in human osteosarcoma." (PMID 29363485, 2018). "As epidermal growth factor receptor (EGFR) positively correlates with TNM (tumor-node-metastasis) stage in osteosarcoma, EGFR may play an important role in its progression." (PMID 29751634, 2018). "Our study demonstrated that SPC24 activated EGFR/Ras/ERK signal pathway in osteosarcoma cells." (PMID 29285250, 2017). "Erlotinib treatment promoted modest enhancement of radiation effects in canine osteosarcoma cells, and possessed activity as a single agent in some cell lines, indicating a potential role for EGFR inhibition in the treatment of a subset of osteosarcoma patients." (PMID 27245053, 2016). "Also in other cellular stress conditions - including very sparse seeding in clonogenic assays and chemotherapy-induced cytotoxicity - EGFR-mediated signals supported osteosarcoma cell survival." (PMID 26526352, 2015). "Consequently, combination approaches including EGFR inhibitors should be evaluated for treatment of high-grade osteosarcoma patients." (PMID 26526352, 2015). "Furthermore, we have demonstrated in our previous study that TGF-α mRNA and protein level were higher in osteosarcoma cell lines and that TGF-α promotes osteosarcoma metastasis through its interaction with EGFR." (PMID 26503469, 2015). "Moreover, osteosarcoma cell migration was significantly reduced by EGFR blockade and this effect was synergistically enhanced in combination with chemotherapy." (PMID 26526352, 2015). "EGFR expression has even been proven to predict poor outcome in osteosarcoma." (PMID 26503469, 2015). "Thus, we investigated combination of EGFR inhibition by gefitinib with osteosarcoma standard chemotherapeutics." (PMID 26526352, 2015).
osteosarcoma (continued). "Moreover, blockade of EGFR by gefitinib inhibited osteosarcoma cell proliferation at standard culture conditions only at comparably high concentrations not likely to be reached in vivo." (PMID 26526352, 2015). "Additionally, targeting of EGFR by cetuximab was suggested to induce osteosarcoma growth inhibition via antibody-dependent tumor cell phagocytosis by a M2-like macrophage subpopulation." (PMID 26526352, 2015). "The expression of EGFR was detected in the vast majority of osteosarcoma." (PMID 26050198, 2015). "In accordance with previous studies on human osteosarcoma cell lines and tissues, we found frequent and profound expression of EGFR in osteosarcoma cells suggesting that it might be an attractive therapy target." (PMID 26526352, 2015). "However, the actual functional contribution of EGFR to osteosarcoma cell biology has remained widely unexplored and literature regarding its prognostic value is contradictory." (PMID 26526352, 2015). "Because AREG supplementation can increase EGFR activity, which consequently enhances osteosarcoma cell migration, we speculated whether the PI3K/Akt signaling pathway mediates the AREG-induced cell migration." (PMID 26503469, 2015). "Consequently, combination approaches of EGFR inhibitors in addition to chemotherapy should be evaluated for treatment of high-grade osteosarcoma patients." (PMID 26526352, 2015). "In our study we could demonstrate functionality of the EGFR in osteosarcoma cell lines leading to EGF-mediated activation of the MAPK and PI3K/AKT pathways." (PMID 26526352, 2015). "The impact of a combined application of the EGFR inhibitor gefitinib with standard chemotherapy used in osteosarcoma cells (e.g. doxorubicin, MTX, cisplatin) was tested for short- and long-term exposure by MTT (72 h) and clonogenic (7 days) assays, respectively." (PMID 26526352, 2015). "Instead, in our experiments, IL-10–polarized M2-like macrophages could be induced to inhibit osteosarcoma cell growth if the tumor cells were coated with the therapeutic anti-EGFR antibody cetuximab." (PMID 24612598, 2014). "Erlotinib, another EGFR inhibitor, has also been reported to be well tolerated in children with solid tumors, but to lack significant antitumor activity against rhabdomyo- or osteosarcomas." (PMID 23227212, 2012). "Therefore, we speculated that DUSP3 affects the stemness of osteosarcoma cells by regulating the EGFR/STAT3/SOX2 axis." (PMID 39744427, 2025). "Also the increased EGFR can rapid the malignant process of osteosarcoma." (PMID 38434350, 2024). "ZR2002 may well represent a good drug candidate for the treatment of EGFR-expressing osteosarcoma." (PMID 36980255, 2023). "Hence, the present study aimed to investigate whether ononin inhibits osteosarcoma cell migration, invasion and proliferation through EGFR-Erk1/2 and MMP2/9 in MG-63, and U2OS and MG-63 xenograft mice." (PMID 36765716, 2023). "However, treating osteosarcoma cell lines with gefitinib improved the effect of methotrexate and doxorubicin, leading the authors to conclude that EGFR may contribute to chemotherapy resistance." (PMID 32961800, 2020). "In addition, certain clinical reports have established that EGFR antibody could aid in the treatment of advanced osteosarcoma." (PMID 29363485, 2018). "To test whether AREG increased the cell migration of osteosarcoma through EGFR, we reduced the EGFR expression by transfecting EGFR siRNA and found that EGFR siRNA inhibited the AREG-induced cancer cell migration and inhibited the AREG-induced ICAM-1 upregulation of the mRNA level." (PMID 26503469, 2015). "Our results showed that DUSP3 binds to EGFR, inhibiting its phosphorylation, thereby regulating STAT3/SOX2 axis and affecting osteosarcoma cell stemness." (PMID 39744427, 2025).
osteosarcoma (continued). "Through modulating the EGFR/STAT3/SOX2 axis, DUSP3 restrains osteosarcoma cell growth, migration, invasion, and stemness." (PMID 39744427, 2025). "Six of these genes are increased (MYOM2, VEGFA, MUC1, IHH, GLI1 and GRIA1) and seven are decreased (VCAM1, EGFR, GPC3, IGF2, GNG12, GNGT1 and C3) in localized patients with poor prognosis that either relapse or die due to osteosarcoma." (PMID 38538763, 2024). "In this study, a total of four transcriptional osteosarcoma-related DNA sequences were screened out, which were mTOR, OGG1, EGFR, and PDGFR-β." (PMID 37065446, 2023). "AREG upregulates ICAM-1 expression via EGFR/PI3K/Akt/NF-κB signaling and promotes the cancer cell viability of osteosarcoma." (PMID 36843929, 2023). "A recent study has demonstrated that Jab1/CSN5 enhances epidermal growth factor receptor (EGFR) stability by decreasing EGFR ubiquitination, thereby activating the PI3K/AKT signaling pathway in osteosarcoma cells." (PMID 35315259, 2022). "The combination therapy of Na131I-labeled and DOX-loaded PLGA nanoparticles is the first study to research the effects of treating MG-63 osteosarcoma with the co-administration of DOX and Na131I in an anti-EGFR targeted PLGA nanotherapeutic." (PMID 36234645, 2022). "Our results confirmed that SCD3, EGFR, and MXI1 were remarkably up-regulated while CAVIN1 and TES were prominently down-regulated in U2OS osteosarcoma cells compared with hFOB1.19 normal cells." (PMID 35071320, 2021). "Its upregulation concomitantly induced activation of AKT through the TGFβ pathway and regulation of EGFR activity and was highly correlated with epithelial-mesenchymal transition (EMT) and resistance to erlotinib in osteosarcoma cancer stem cell–like cells." (PMID 34616428, 2021). "TGF-α/EGFR interacted PI3K/Akt activation, then activated NF-κB, increased the expression of ICAM-1, and contributed to the migration of human osteosarcoma cells." (PMID 33436536, 2021). "EGFR-immobilized Sali-loaded nanoparticles proved more effective in inhibiting the proliferation of U2O2 and MG-63 osteosarcoma cells and reducing the tumorsphere formation rate than the nontargeted nanoparticles and free Sali." (PMID 34452081, 2021). "In the five-gene signature, we separately evaluated the prognostic potential of CAVIN1, EGFR, SCD3, TES, and MXI1 in osteosarcoma." (PMID 35071320, 2021). "Epidermal growth factor (EGF) promotes cell epithelial-mesenchymal transition, metastasis, and progression of osteosarcoma by activating MAPK and PI3K/AKT pathway, which can be blocked by the EGFR-specific inhibitor gefitinib." (PMID 32665038, 2020). "A bispecific antibody targeting IGF-1R and EGFR was able to inhibit tumour growth and prevent lung metastases in a mouse osteosarcoma model, suggesting that it may have potential as a therapy for metastatic osteosarcoma, though this has yet to be tested clinically." (PMID 32961800, 2020). "EGFR and p-ERK expression decreased significantly after Spc24 gene knockout, and osteosarcoma cell growth was significantly inhibited." (PMID 32322168, 2020). "Intriguingly, gefitinib, an epidermal growth factor receptor (EGFR) inhibitor, altered pulmonary macrophage phenotype to block osteosarcoma invasion and reduce metastatic burden via inhibition of macrophage receptor-interacting protein kinase 2 (RIPK2)." (PMID 33363016, 2020). "In conclusion, our data showed that SC, a cantharidin derivative, inhibited osteosarcoma progression in vitro and in vivo and abrogated the feedback activation of STAT3 induced by EGFR inhibition." (PMID 31422383, 2019). "Activation of EGFR would bypass the EGFR/JAK/STAT3 axis, initiate other downstream signalling pathways, and compensate for the inactivation of STAT3, favoring osteosarcoma growth and progression." (PMID 31422383, 2019). "Abnormal EGFR expression and constitutive STAT3 activation have been described in osteosarcoma cells in relation to disease progression and chemotherapy resistance." (PMID 31422383, 2019).